RNF185 (ring finger protein 185)
Description:
E3 ubiquitin-protein ligase that regulates selective mitochondrial autophagy by mediating 'Lys-63'-linked polyubiquitination of BNIP1. Acts in the endoplasmic reticulum (ER)- associated degradation (ERAD) pathway, which targets misfolded proteins that accumulate in the endoplasmic reticulum (ER) for ubiquitination and subsequent proteasome-mediated degradation. Protects cells from ER stress-induced apoptosis. Responsible for the cotranslational ubiquitination and degradation of CFTR in the ERAD pathway. Also acts as a regulator of the innate antiviral response by catalyzing 'Lys-27'-linked polyubiquitination of CGAS at 'Lys-173' and 'Lys-384', thereby promoting CGAS cyclic GMP-AMP synthase activity. Preferentially associates with the E2 enzymes UBE2J1 and UBE2J2.
Synonyms: FLJ38628
Tractability: Antibody: UniProt predicts a signal peptide or a membrane-spanning region. PROTAC: ubiquitination databases record sites on it.
Gene: Protein-coding gene on chromosome 22 (31,160,158 to 31,207,019, forward strand). Ensembl gene ENSG00000138942.
Subcellular location: Mitochondrion outer membrane; Endoplasmic reticulum membrane
Pathways (Reactome):
Disease: Defective CFTR causes cystic fibrosis
Immune System: AMPK-induced ERAD and lysosome mediated degradation of PD-L1(CD274)
Metabolism of proteins: ER Quality Control Compartment (ERQC)
Transport of small molecules: ABC-family protein mediated transport
Gene Ontology:
Molecular function: protein binding; protein-containing complex binding; ubiquitin binding; ubiquitin protein ligase activity; ubiquitin-like protein conjugating enzyme binding; metal ion binding; ubiquitin-protein transferase activity
Biological process: defense response to virus; ERAD pathway; positive regulation of ERAD pathway; positive regulation of innate immune response; positive regulation of type I interferon-mediated signaling pathway; protein autoubiquitination; protein K27-linked ubiquitination; ubiquitin-dependent protein catabolic process; endoplasmic reticulum mannose trimming; transmembrane transport; protein ubiquitination
Cellular component: endoplasmic reticulum; endoplasmic reticulum membrane; mitochondrial outer membrane; cytoplasm; endoplasmic reticulum quality control compartment
Genetic constraint (gnomAD): Loss-of-function variants: 7 observed, 12.54 expected, observed/expected ratio (o/e) 0.56, 90% interval 0.32 to 1.05. The upper end of that interval is the gene's LOEUF score, 1.05, which puts it in group 4 of 6, group 1 being the genes least tolerant of losing a copy. Missense variants: 145 observed, 177.49 expected, observed/expected ratio (o/e) 0.82, 90% interval 0.71 to 0.94. Synonymous variants: 57 observed, 66.56 expected, observed/expected ratio (o/e) 0.86, 90% interval 0.69 to 1.07.
Homologues: Orthologues: pig RNF185 (100% identical), rabbit RNF185 (100% identical), rat Rnf185 (99% identical), mouse Rnf185 (98% identical), guinea pig RNF185 (98% identical), zebrafish rnf185 (88% identical), tropical clawed frog rnf185 (87% identical), chimpanzee RNF185 (80% identical), Drosophila melanogaster sordd1 (57% identical), Drosophila melanogaster sordd2 (54% identical), Caenorhabditis elegans rnf-5 (49% identical), Drosophila melanogaster CG32847 (38% identical). Paralogues in human: RNF5 (56% identical).
Diseases named in the same sentence as RNF185 in open-access papers:
RNF185 is named in the same sentence as 16 diseases in open-access papers, as found by Europe PMC text mining. Sharing a sentence is not in itself a finding about the gene and the disease. The quoted sentences say what the papers report.
gastric cancer (4 papers, 2022 to 2025). A primary or metastatic malignant neoplasm involving the stomach. "In this regard, inhibition of ring finger protein 185 (RNF185) was found to inhibit the metastasis of gastric cancer." (PMID 40253526, 2025). "Interestingly, though the function of RNF185 was shown to promote gastric cancer, our screening results in U87 cells showed RNF185 as a tumor suppressor." (PMID 35183197, 2022). "Moreover, RNF185 was proved to promote gastric cancer metastasis, while its role in glioma remains to be explored." (PMID 35183197, 2022). "The PKC phosphorylation motif of JWA is responsible for the activation of the MEK-ERK pathway and cell migration; in gastric cancer, JWA lysine 158 is a necessary site for RING Finger Protein 185 (RNF185) ubiquitination and degradation of JWA." (PMID 36230577, 2022). "Thus, RNF185 could play an oncogenic role in gastric cancer (GC)." (PMID 38139010, 2023).
glioma (4 papers, 2021 to 2024). A benign or malignant brain and spinal cord tumor that arises from glial cells (astrocytes, oligodendrocytes, ependymal cells). "At last, the transcription molecular events of RNF185 in glioma were analyzed, and the histone activation marks and DNase-Seq peaks in the promoter region of RNF185 was analyzed in fetal brain, adult brain and glioma cells U87 and U251." (PMID 35183197, 2022). "Taken together, elevated miR-587 expression contributes to the decreased expression of RNF185 and promotes glioma proliferation, migration and reduces cell apoptosis." (PMID 35183197, 2022). "So, we further validated the function of RNF185 in other glioma cell lines, U251 and DBTRG, with overexpression strategy." (PMID 35183197, 2022). "In vitro overexpressed cellular phenotype showed that RNF185 was a tumor suppressor in two glioma cell lines." (PMID 35183197, 2022). "Taken together, we conclude that combined transcriptional repression and elevated miR-587 expression may reduce the RNF185 mRNA expression in glioma." (PMID 35183197, 2022). "Histone transactivation marks peaks in fetal, adult brain and glioma cells shows that RNF185 may also under the transcriptional repression, with development and glioblastoma pathogenesis." (PMID 35183197, 2022). "Next, to explore whether miR-587 regulate RNF185 expression, we examined the expression of RNF185 in miR-587 inhibitor treated glioma cells." (PMID 35183197, 2022). "The strong negative correlation of methylation with mRNA expression suggests that promoter hypermethylation may play an important role for the decreased expression of RNF185 in glioma samples." (PMID 35183197, 2022). "Strong peak signals were observed in fetal brain, followed by adult brain and glioma cells, suggesting that RNF185 may also under transcriptional repression in glioma." (PMID 35183197, 2022). "Consistent with previous studies, BIRC3 and RNF135 were all previously reported as oncogenes in glioma, while we first revealed that RNF185 may play a tumor suppressor role in glioblastoma." (PMID 35183197, 2022). "BIRC3, KLHL10 and RNF135 showed unfavorable biomarker performance in glioma samples, and only RNF185 may serve as a favorable marker." (PMID 35183197, 2022). "In order to explore miRNAs that may regulate RNF185 expression in glioma, we first predicted miRNAs with three online tools: miRWalk, TargetScan and miRDB." (PMID 35183197, 2022). "Mechanistically, the study found that RNF185 expression is reduced in glioma due to promoter hypermethylation and increased expression of the oncogenic miRNA miR-587, which directly targets the 3‘UTR of RNF185." (PMID 38891890, 2024). "Of the 3 genes (BIRC3, RNF135 and RNF185) with both differential expression and prognostic significance, BIRC3 and RNF135 were all previously reported as oncogenes in glioma." (PMID 35183197, 2022). "MiR-587 inhibitors phenol-copied the cell proliferation, apoptosis and migration and invasion function of RNF185 overexpressed U251 and DBTRG cells, implying that miR-587 play an oncogenic role in glioma." (PMID 35183197, 2022).
systemic lupus erythematosus (3 papers, 2017 to 2022). An autoimmune multi-organ disease typically associated with vasculopathy and autoantibody production. "Additionally, Systemic Lupus Erythematosus (SLE) patients displayed elevated expression of RNF185 mRNA." (PMID 28273161, 2017). "The E3 ligase RNF185, expression of which is upregulated in Systemic Lupus Erythematosus (SLE) patients, has been shown to be involved in the regulation of cGAS activity." (PMID 29546673, 2018). "The patients suffering from Systemic Lupus Erythematosus (SLE), has constitutive activation of cGAMP-STING signaling, and displayed elevated expression of RNF185 mRNA." (PMID 36139387, 2022). "Notably, systemic lupus erythematosus (SLE) patients have elevated expression of RNF185 mRNA." (PMID 28273161, 2017).
prostate carcinoma (2 papers, 2023 to 2025). A carcinoma that arises from epithelial cells of the prostate gland. "Downregulation of RNF185 expression has been found to correlate with prostate cancer progression and metastasis, and when RNF185 is reduced, the wound healing and cellular movement pathways were the most significant that were found upregulated." (PMID 38139010, 2023). "Collagen type III alpha 1 chain (COL3A1) has been identified as the main mediator of RNF185’s ability to promote the migration phenotype in prostate cancer cells as COL3A1 inhibition was capable of attenuating the migration and metastasis of the cancer cells." (PMID 38139010, 2023). "Thus, the replenishment of RNF185 or the targeting of COL3A1 may be considered as possible strategies for prostate cancer therapy." (PMID 38139010, 2023). "A further possible strategy to inhibit CYP51A1TM indirectly could be represented by the modulation of RNF185 activity, such as via gene therapy, for those cancers where it is underexpressed (i.e., HCC, PTC, prostate carcinoma)." (PMID 38139010, 2023).
renal cell carcinoma (2 papers, 2021 to 2023). "In addition, the expression levels of RNF185 are positively associated with the lymph node and distant metastasis in renal cell carcinomas patients." (PMID 35111198, 2021). "Moreover, RNF185 total serum cell-free DNA concentrations have been found higher in patients with renal cell carcinoma (RCC) than in patients with benign tumors." (PMID 38139010, 2023).
viral infections (2 papers, 2018 to 2023). "Ring finger protein 185 (RNF185, an E3 ubiquitin ligase) interacts with cGAS during viral infections and specifically catalyzes the K27-linked polyubiquitination of cGAS at K137 and K384, enhancing the enzymatic activity of cGAS37." (PMID 36964253, 2023). "Much is known of RNF185, especially about its role associated with viral infections." (PMID 29867845, 2018).
autoimmune disease (1 paper, 2025). A disorder resulting from loss of function or tissue destruction of an organ or multiple organs, arising from humoral or cellular immune responses of the individual to their own tissue constituents. "SLE, the E3 ubiquitin ligase RNF185 induces hyperactivation of the pathway associated with autoimmune disorders." (PMID 40028324, 2025). "In autoimmune diseases like SLE, the overactivation of the cGAS-STING pathway can lead to excessive immune responses, with RNF185 being a key E3 ubiquitin ligase implicated in SLE pathogenesis." (PMID 40028324, 2025).
breast carcinoma (1 paper, 2024). "Taken together, D-mannose increases the expression of RNF185 in breast cancer cells through AMPK acitivation." (PMID 38167476, 2024). "In this study, we found that D-mannose treatment can promote the degradation of IDH2 protein in mammary cancer cells by upregulating the E3 ligase RNF185, rendering the tumor cells more vulnerable to pro-oxidant treatment and inhibiting the proliferation of breast cancer cells." (PMID 38167476, 2024).
cystic fibrosis (1 paper, 2022). Autosomal recessive disorder caused by pathogenic variants in the CFTR gene (cystic fibrosis transmembrane conductance regulator), which encodes a chloride and bicarbonate channel expressed in epithelial cells, and follow the diagnosis criteria. "Ring Finger Protein 185 (RNF185) has been shown to regulate cell autophagy, innate immune responses, osteogenic differentiation and cystic fibrosis." (PMID 35183197, 2022).
glioblastoma (1 paper, 2022). The most malignant astrocytic tumor (WHO grade IV). "After validating the RNF185 as a tumor suppressor in glioblastoma, we interrogated the molecular basis for its decreased expression." (PMID 35183197, 2022). "This is the first time we prove miR-587 as a tumor promoting miRNA in glioblastoma by targeting RNF185." (PMID 35183197, 2022). "First, further in-vivo evidence would make the conclusion that RNF185 play a tumor surpassing role in glioblastoma more solid." (PMID 35183197, 2022). "Finally, the strategy of delivering RNF185 for glioblastoma treatment would provide more information for the future clinical application." (PMID 35183197, 2022). "Secondly, the substrate and exact functional way of RNF185 in glioblastoma remain to be revealed." (PMID 35183197, 2022). "Moreover, we also studied the transcriptional regulators of RNf185 in glioblastoma samples." (PMID 35183197, 2022).
retinal degeneration (1 paper, 2020). Degeneration of the retina. "Furthermore, ERAD of misfolded proteins via SORDD1 is likely conserved in mammals, as RNF5 and RNF185 also suppressed Rh1G69D-induced retinal degeneration." (PMID 33137101, 2020).
thyroid cancer (1 paper, 2023). "On the other hand, when two mito E3s act as tumor suppressors (such as in thyroid cancer for RNF185 and MUL1), induction of both enzymes could achieve a synergistic effect on cancer inhibition." (PMID 38139010, 2023).
tumor (5 papers, 2017 to 2024). "To further validate the role of RNF185-IDH2 axis in D-mannose mediated inhibition of tumor cell proliferation, we knocked down RNF185 in MDA-MB-231 cells and examined its effects on NADPH production and cell proliferation." (PMID 38167476, 2024). "Based on the reviewed literature, MARCH5 has mostly an oncogenic role, RNF185 acts as a tumor suppressor, whereas MUL1 can have both roles depending on the cell type." (PMID 38139010, 2023). "Collectively, this study shows that Ring Finger Protein 185 as a novel tumor suppressor in glioma multiforme, which is repressed by promoter hypermethylation and miR-587." (PMID 35183197, 2022). "Future investigation is expected to uncover the potential roles of RNF185 in mitochondrial stress, DNA damage, and tumor immunity." (PMID 28273161, 2017). "Similarly, the inhibition of tumor cell proliferation by D-mannose was rescued under RNF185 knockdown." (PMID 38167476, 2024). "Interestingly, our screening results in U87 cells showed RNF185 as a tumor suppressor." (PMID 35183197, 2022). "Together, we concluded that D-mannose mediated RNF185 upregulation plays a key role in IDH2 degradation and tumor cell inhibition." (PMID 38167476, 2024). "RNF185 is an RNF5 homolog, and RNF5 has been found to exert pro- or anti-tumor activity depending on the tumor model." (PMID 38139010, 2023). "This review will highlight the different roles of MARCH5, RNF185 and MUL1 in cancer, focusing on their functions as potential oncogenes or tumor suppressors and defining a possible use for therapy." (PMID 38139010, 2023). "Furthermore, when RNF185 was knocked down, the inhibition effect of BSO and D-mannose combination on tumor cells was partially abrogated, and the relative survival of tumor cells showed significant improvement." (PMID 38167476, 2024). "As shown by the reviewed studies below, RNF185 has been shown to act as a tumor suppressor, and thus, its lack of function is reflected in the development of cancer." (PMID 38139010, 2023). "On this basis, it can be hypothesized that RNF185, in a COL3A1-dependent manner, may act as a tumor suppressor in a broad spectrum of cancers; consequently, it may be targeted for the development of therapeutic strategies for different tumors." (PMID 38139010, 2023).
cancer (4 papers, 2020 to 2022). A tumor composed of atypical neoplastic, often pleomorphic cells that invade other tissues. "The seemingly contradictory function of RNF185 has also been observed in other E3 ubiquitin ligases in different cancer types." (PMID 35183197, 2022). "The converse function of RNF185 may be attributed to its substrates in distinct cancer types." (PMID 35183197, 2022). "Our rnf185 and rnf215 zebrafish mutants may be used for cancer genetic studies in the future." (PMID 31915253, 2020). "To assess the expression of Gp78 in multiple cancers, we used GEPIA-2 analysis to probe TCGA RNAseq data for mRNA expression of Gp78 and other ubiquitin ligases that induce mitophagy (PARK2, RNF185, MUL1, MARCH5, HUWE1, SIAH1) as well as the hypoxia-induced mitophagy proteins BNIP and NIX." (PMID 36284011, 2022).
infection (2 papers, 2017 to 2019). The state of being infected such as from the introduction of a foreign agent such as serum, vaccine, antigenic substance or organism. "In contrast, the abundance of Ifnb, Ifna4 or Cxcl10 mRNAs induced by RNA mimic poly(I:C) transfection or RNA virus Sendai virus (SeV) infection was comparable between Rnf185 knockdown and wild-type L929 cells." (PMID 28273161, 2017). "We found that ISG15, OASl-1, and RNF185 were induced in A549 cells infected with D39 at 1 h, but not 5 h post-infection." (PMID 30984149, 2019). "(a) Knocking down RNF185 specifically attenuated the expression of IRF3-responsive genes induced by DNA mimics transfection or DNA virus HSV-1 infection, but not by RNA mimic transfection or RNA virus SeV infection." (PMID 28273161, 2017).
RNF185 also shares sentences with these, for which no sentence is quoted: autoimmune disorders (1 paper).